CCDC182 (coiled-coil domain containing 182)
Tractability: No criterion of Open Targets' tractability assessment is met for any kind of drug.
Gene: Protein-coding gene on chromosome 17 (57,744,495 to 57,745,299, reverse strand). Ensembl gene ENSG00000166329.
Gene Ontology:
Biological process: female gonad development
Genetic constraint (gnomAD): Loss-of-function variants: 5 observed, 9.36 expected, observed/expected ratio (o/e) 0.53, 90% interval 0.28 to 1.12. That is too few expected variants to judge how well the gene tolerates losing a copy. Missense variants: 209 observed, 197.03 expected, observed/expected ratio (o/e) 1.06, 90% interval 0.95 to 1.19. Synonymous variants: 82 observed, 86.7 expected, observed/expected ratio (o/e) 0.95, 90% interval 0.79 to 1.14.
Homologues: Orthologues: chimpanzee CCDC182 (99% identical), macaque CCDC182 (97% identical), pig CCDC182 (86% identical), guinea pig CCDC182 (85% identical), dog CCDC182 (84% identical), mouse Ccdc182 (83% identical), rabbit CCDC182 (82% identical), rat Ccdc182 (82% identical).